PSMD13 (proteasome 26S subunit, non-ATPase 13)
Description:
Component of the 26S proteasome, a multiprotein complex involved in the ATP-dependent degradation of ubiquitinated proteins. This complex plays a key role in the maintenance of protein homeostasis by removing misfolded or damaged proteins, which could impair cellular functions, and by removing proteins whose functions are no longer required. Therefore, the proteasome participates in numerous cellular processes, including cell cycle progression, apoptosis, or DNA damage repair.
Synonyms: p40.5; Rpn9; HSPC027; S11
Tractability: Small molecule: an approved drug acts on it; a structure with a bound ligand is known; a high-quality ligand is known. Antibody: its Gene Ontology location is reachable by antibodies, with high confidence. PROTAC: ubiquitination databases record sites on it; its protein half-life has been measured.
Target class: Enzyme
Gene: Protein-coding gene on chromosome 11 (236,966 to 252,986, forward strand). Ensembl gene ENSG00000185627.
Subcellular location (Human Protein Atlas): Nuclear speckles; Cytosol
Pathways (Reactome):
Immune System: AMPK-induced ERAD and lysosome mediated degradation of PD-L1(CD274); Activation of NF-kappaB in B cells; Antigen processing: Ubiquitination & Proteasome degradation; CLEC7A (Dectin-1) signaling; Cross-presentation of soluble exogenous antigens (endosomes); Dectin-1 mediated noncanonical NF-kB signaling; Downstream TCR signaling; ER-Phagosome pathway; FCERI mediated NF-kB activation; GSK3B-mediated proteasomal degradation of PD-L1(CD274); Interleukin-1 signaling; NIK-->noncanonical NF-kB signaling; Neutrophil degranulation; SPOP-mediated proteasomal degradation of PD-L1(CD274); TNFR2 non-canonical NF-kB pathway
Cell Cycle: APC/C:Cdc20 mediated degradation of Securin; APC/C:Cdh1 mediated degradation of Cdc20 and other APC/C:Cdh1 targeted proteins in late mitosis/early G1; Autodegradation of Cdh1 by Cdh1:APC/C; Autodegradation of the E3 ubiquitin ligase COP1; Cdc20:Phospho-APC/C mediated degradation of Cyclin A; FBXL7 down-regulates AURKA during mitotic entry and in early mitosis; G2/M Checkpoints; SCF(Skp2)-mediated degradation of p27/p21; SCF-beta-TrCP mediated degradation of Emi1; Separation of Sister Chromatids; The role of GTSE1 in G2/M progression after G2 checkpoint; Ubiquitin-Mediated Degradation of Phosphorylated Cdc25A; Ubiquitin-dependent degradation of Cyclin D
Signal Transduction: Asymmetric localization of PCP proteins; Degradation of AXIN; Degradation of DVL; Degradation of GLI1 by the proteasome; Degradation of GLI2 by the proteasome; Degradation of beta-catenin by the destruction complex; GLI3 is processed to GLI3R by the proteasome; Hedgehog 'on' state; Hedgehog ligand biogenesis; MAPK6/MAPK4 signaling; Negative regulation of NOTCH4 signaling; Regulation of PTEN stability and activity
and 28 more pathways
Gene Ontology:
Molecular function: protein binding; structural molecule activity
Biological process: cellular response to type I interferon; proteasomal protein catabolic process; proteasome-mediated ubiquitin-dependent protein catabolic process; regulation of proteasomal protein catabolic process; response to oxidative stress; ubiquitin-dependent protein catabolic process
Cellular component: membrane; nucleus; proteasome complex; cytosol; extracellular region; ficolin-1-rich granule lumen; nucleoplasm; proteasome accessory complex; proteasome regulatory particle; proteasome regulatory particle, lid subcomplex; secretory granule lumen; synaptic vesicle; protein-containing complex
Genetic constraint (gnomAD): Loss-of-function variants: 8 observed, 58.62 expected, observed/expected ratio (o/e) 0.14, 90% interval 0.079 to 0.25. The upper end of that interval is the gene's LOEUF score, 0.25, which puts it in group 1 of 6, group 1 being the genes least tolerant of losing a copy. Missense variants: 378 observed, 464.44 expected, observed/expected ratio (o/e) 0.81, 90% interval 0.75 to 0.89. Synonymous variants: 185 observed, 170.87 expected, observed/expected ratio (o/e) 1.08, 90% interval 0.96 to 1.22.
Homologues: Orthologues: chimpanzee PSMD13 (99% identical), dog PSMD13 (99% identical), pig PSMD13 (98% identical), mouse Psmd13 (97% identical), macaque PSMD13 (90% identical), tropical clawed frog psmd13 (87% identical), rat Psmd13 (86% identical), zebrafish psmd13 (80% identical), guinea pig PSMD13 (73% identical), Drosophila melanogaster Rpn9 (45% identical), Caenorhabditis elegans rpn-9 (41% identical).
Diseases named in the same sentence as PSMD13 in open-access papers:
PSMD13 is named in the same sentence as 22 diseases in open-access papers, as found by Europe PMC text mining. Sharing a sentence is not in itself a finding about the gene and the disease. The quoted sentences say what the papers report.
depression (4 papers, 2015 to 2025). "This study found that subjects carrying the homozygous GG genotype of PSMD13 rs3817629 had a twofold greater risk of developing treatment-resistant depression compared to those carrying the A allele of PSMD13." (PMID 39940735, 2025). "Another case-control study (622 MDD patients, of whom 390 had treatment-resistant depression) conducted an association study for the proteasome subunit PSMD13 and analyzed peripheral blood samples." (PMID 39940735, 2025). "The PSMD13 rs3817629 G allele was found to be associated with treatment-resistant depression." (PMID 34321460, 2021).
Epstein-Barr virus infection (2 papers, 2017 to 2022). An infection that is caused by Epstein-Barr virus. "Finally, four significant KEGG enrichment pathways were identified (P < 0.05): beta-Alanine metabolism (SMOX, HIBCH), Pathways in cancer (GLI2, AR, TXNRD3, TRAF3, FGF16), Non-homologous end-joining (MRE11), Epstein-Barr virus infection (TRAF3, PSMD13, SIN3A)." (PMID 36330154, 2022). "Finally, the results of KEGG enrichment analysis showed four significantly enriched pathways (P < 0.05): beta-Alanine metabolism (SMOX, HIBCH), Pathways in cancer (GLI2, AR, TXNRD3, TRAF3, FGF16), Non-homologous end-joining (MRE11), Epstein-Barr virus infection (TRAF3, PSMD13, SIN3A)." (PMID 36330154, 2022).
breast carcinoma (1 paper, 2022). "Here, we validated the role of Psmd13 for breast cancer cell growth in vitro by showing reduced MTT viability and colony growth upon targeting." (PMID 36313646, 2022). "Many of those hits were supported by literature, whereby some hits were so far overlooked in the context of breast cancer (e.g., Lonp1, Uspl1) or cancer in general (e.g., Psmd13, Tysnd1)." (PMID 36313646, 2022).
clear cell renal carcinoma (1 paper, 2023). A malignant epithelial neoplasm of the kidney characterized by the presence of lipid-containing clear cells within a vascular network. "At lower frequencies, missense mutations in PSMD13 have also been reported in MPM tumors and in whole-exome sequencing studies, including 2680 melanoma, mesothelioma, and clear-cell renal carcinoma samples." (PMID 36980270, 2023).
colon cancer (1 paper, 2024). "Previously, PSMD13 was upregulated in SW480 and SW620 colon cancer cells upon oxaliplatin treatment, leading to growth suppression and apoptosis." (PMID 38542474, 2024).
DiGeorge Syndrome (1 paper, 2022). "SROs with candidate genes were found in the established risk loci for other syndromes known to be associated with hypospadias, such as Silver–Russell Syndrome (PSMD13); 13q Deletion Syndrome (COL4A1); and 22q Deletion/Duplication Syndromes, which includes DiGeorge Syndrome (CRKL)." (PMID 35457073, 2022).
glioma (1 paper, 2022). A benign or malignant brain and spinal cord tumor that arises from glial cells (astrocytes, oligodendrocytes, ependymal cells). "Among them, PCOLCE2, ERP27, PSMD13, C14orf39, C16orf86, UGCG, and HPX were identified as prognostic factors for glioma for the first time." (PMID 35873494, 2022).
lung adenocarcinoma (1 paper, 2022). A carcinoma that arises from the lung and is characterized by the presence of malignant glandular epithelial cells. "PSMD13 expression in lung adenocarcinoma strongly correlates with PSMC6 expression, which is associated with poor tumor differentiation and might act as a therapeutic target in lung adenocarcinoma." (PMID 35873494, 2022).
spinocerebellar ataxia (1 paper, 2025). "Among the most significantly enriched proteins within the spinocerebellar ataxia pathway were proteasome 26S subunit (PSMD1, PSMD7, PSMD12, PSMD13), specifically the non-ATPase regulatory components, which are central to the degradation of ubiquitinated proteins." (PMID 41441337, 2025).
varicocele (1 paper, 2020). A condition characterized by the dilated tortuous veins of the spermatic cord with a marked left-sided predominance. "All the DEPs overexpressed in the spermatozoa of men with bilateral varicocele compared to underexpressed proteins in unilateral varicocele were present in a high abundance except for AKR1B1 and PSMD13." (PMID 32365753, 2020).
vitiligo (1 paper, 2025). Generalized well circumscribed patches of leukoderma that are generally distributed over symmetric body locations and is due to autoimmune destruction of melanocytes. "Our work underscores the importance of HMGA1 and PSMD13 in the pathophysiological mechanisms underlying vitiligo, potentially opening new avenues for both diagnostic and treatment strategies for this condition." (PMID 40443672, 2025). "PSMD13 may influence vitiligo development via the Nod-like receptor signaling pathway and could serve as a potential diagnostic marker for evaluating skin lesions in vitiligo." (PMID 40443672, 2025). "Despite their potential importance, research into the specific functions of HMGA1 and PSMD13 within the context of vitiligo remains scarce." (PMID 40443672, 2025). "The expression levels of the overlapping hub genes HMGA1 and PSMD13 in the peripheral blood of vitiligo patients and control patients were assessed via qRT–PCR." (PMID 40443672, 2025). "Our study revealed a decrease in PSMD13 expression within the blood samples of vitiligo patients, corroborated by a consistent downwards trend observed in follow-up validations using lesional skin datasets." (PMID 40443672, 2025). "In summary, we identified two vitiligo-associated genes, HMGA1 and PSMD13, via WGCNA and machine learning approaches on datasets GSE80009 and GSE90880." (PMID 40443672, 2025). "This study identified PSMD13 and HMGA1 as potential hub genes linked to vitiligo using integrated bioinformatics and experimental validation." (PMID 40443672, 2025). "Our study explored the potential of HMGA1 and PSMD13 as markers for vitiligo; these results validate our findings and have practical implications for the diagnosis and treatment of vitiligo." (PMID 40443672, 2025). "This study identified two key genes, HMGA1 and PSMD13, in the blood of vitiligo patients using bioinformatics and machine learning techniques." (PMID 40443672, 2025). "In addition, PSMD13 significantly decreased in the lesioned skin of vitiligo patients, suggesting that PSMD13 is involved in the skin lesion development process through the NOD-like-receptor signalling pathway, but HMGA1 did not significantly decrease in the lesioned skin." (PMID 40443672, 2025). "The changes in HMGA1 expression in the inflamed skin of vitiligo patients compared with that in healthy skin were not significant, but PSMD13 expression showed a significant downwards trend." (PMID 40443672, 2025).
cancer (7 papers, 2017 to 2024). A tumor composed of atypical neoplastic, often pleomorphic cells that invade other tissues. "For example, rs1794108 is a missense deleterious mutation in the proteasome 26S subunit, non-ATPase 13 (PSMD13) that is involved in cellular senescence, ageing and with the onset of various cancers." (PMID 29064820, 2017). "In addition, PSMD13 and SIRT3 share a promoter, and PSMD13, a proteasome subunit, is involved in the degradation of abnormal proteins, cellular senescence and ageing and variants in this gene have previously been associated with the onset of various cancers." (PMID 29064820, 2017). "For instance, seven PSM genes (i.e. PSMA1, PSMA4, PSMC1, PSMC3IP, PSMD13, PSMG2-3 (PSM class I/II/V)) were overexpressed in the majority of the 16 cancer types." (PMID 36123629, 2022). "Other depletion hits, such as Psmd13 and the “peroxisomal matrix protein trypsin domain-containing 1” (Tysnd1), have to our knowledge not been postulated to be important for cancer growth." (PMID 36313646, 2022). "Interestingly, BAP1 and PSMD13 genetic alterations do not co-occur in any of the samples reported in these studies, suggesting that the presence of mutations in both genes compromise cell viability, not only in MPM, but also in BAP1-TPDS-related cancer types." (PMID 36980270, 2023).
infection (2 papers, 2014 to 2024). The state of being infected such as from the introduction of a foreign agent such as serum, vaccine, antigenic substance or organism. "Psmd1 and Psmd13, 26S proteasome regulatory subunits, were identified to be significant primarily during secondary infection." (PMID 25341656, 2014). "Therefore, the identification of Psmd1 and Psmd13 in our constructed intracellular PPI networks for secondary infection indicates that the proteasome system plays a pivotal role in the zebrafish immune response." (PMID 25341656, 2014). "Furthermore, the numbers of linkages from primary to secondary infection for both Psmd1 and Psmd13 increased significantly, suggesting that the proteasome is more active during secondary infection, and is therefore more important in the adaptive immune response of zebrafish." (PMID 25341656, 2014).
psychiatric disorder (1 paper, 2015). A disorder characterized by behavioral and/or psychological abnormalities, often accompanied by physical symptoms. "Only one study has shown a putative role of proteasomal PSMA7, PSMD9 and PSMD13 genes in the susceptibility to an antidepressant response, and sparse data are available regarding the potential alterations in proteasome expression in psychiatric disorders such as MDD." (PMID 26624926, 2015).
PSMD13 also shares sentences with these, for which no sentence is quoted: tumor (2 papers); Cachexia (1); diabetes (1); hypospadias (1); malignant pleural mesothelioma (1); melanoma (1); mesothelioma (1); sarcoidosis (1).